SCD (stearoyl-CoA desaturase)
Diseases named in the same sentence as SCD in open-access papers (continued):
Sharing a sentence is not in itself a finding about the gene and the disease.
tumor (continued). "Targeting SCD activity by its specific inhibitors results in tumor-specific apoptosis." (PMID 36472914, 2023). "Such increase of desaturated FA bond(s) in tumor PLs likely reflects the upregulated stearoyl-CoA desaturase activity that introduced the Δ-9 unsaturated bond in palmitoyl and stearoyl FA moieties in the de novo synthesized tumor PCs in bulk and lowered the saturated FA to MUFA ratio." (PMID 36273646, 2022). "A939572-mediated anti-tumor effects were confirmed in SCD-overexpressing NSCLC cells in vivo." (PMID 35159223, 2022). "It was shown that the chemical inhibitor of SCD suppressed tumor growth in mouse model." (PMID 36514170, 2022). "OA (C18:1) is the most abundant uS-FA in plasma 49; therefore, we assumed that exogenous lipids or uS-FAs could compensate for low SCD expression in tumor cells, thus masking the effects of SCD deletion." (PMID 35342344, 2022). "Furthermore, lower expression levels of SCD, SQLE, FADS2 and TFRC were significantly associated with increased tumor infiltration of DCs and/or B cells." (PMID 35818395, 2022). "FABP4 could enhance tumor transport for increased LD content, which coordinates with FA desaturation mediated by stearoyl-CoA desaturase-1 (SCD1), to protect tumor cells from oxidative stress-induced ferroptosis." (PMID 35899119, 2022). "Tumour growth inhibition of mouse xenografts treated with SCD-1 inhibitor could be reversed by administration of a ceramide biosynthesis inhibitor." (PMID 35954376, 2022). "In addition, SCD expression is related to the survival time of patients, which can be used as a marker of tumor prognosis." (PMID 35896782, 2022). "Next, to test whether reducing FOSB levels in advanced SCD inhibitor–treated tumors (when they presumably start acquiring resistance to the inhibitor) exerted any effect on tumor growth and survival, we performed an additional experiment." (PMID 33568479, 2021). "In addition, we validated (i) the co-regulatory feedback loop between SREBF1/TP63/KLF5, and (ii) canonical target genes of SREBF1 in fatty-acid metabolism (e.g., ACLY, FASN, and SCD) in xenograft tumor samples." (PMID 34272396, 2021). "Thus, SCD levels and oxygen availability for their enzymatic reaction to generate unsaturated lipids are critical determinants for tumor growth and survival." (PMID 33580155, 2021). "Tumor cells are heavily dependent on SCD-mediated de novo synthesis of unsaturated fatty acids for their rapid growth, although certain tumors are able to bypass SCD activity by scavenging unsaturated fatty acids from their microenvironments, when oxygen is depleted." (PMID 33580155, 2021). "It was suggested that SCD-1 could be a therapeutic target in oncology, since its pharmacological inhibition induces tumor cell apoptosis." (PMID 34199164, 2021). "Besides, MUFAs generated by overexpressed SCD are tumor-promoting and essential for chemoresistance and recurrence of tumors." (PMID 35006438, 2021). "Here, a prominent upregulation of SCD mRNA levels was observed in all tumor samples." (PMID 34206240, 2021). "In addition, we provided evidence to reinforce the idea that SCD-1 is a meaningful pharmacological target pondering the global hypoxic context of the tumor microenvironment." (PMID 34199164, 2021). "However, when using the GAPDH gene as reference, correlations between the growing tumor area and peritumoral area were found only for SCD and SCD5." (PMID 32392704, 2020). "In our study of GBM tumors, the expression of the SCD gene—one that may play a significant role in the proliferation of rapidly dividing cells—was lower in the growing tumor area and necrotic core than in the peritumoral area." (PMID 32392704, 2020).
tumor (continued). "The occurrence of tumor cells depends on the fluidity, functionality, and flexibility of monounsaturated fatty acids, which also involves the action of stearoyl-CoA desaturase (SCD-1)." (PMID 33096860, 2020). "SCD regulates important survival and proliferation signalling pathways in tumour cells." (PMID 30592142, 2019). "There, skin SCD expression is low; yet among tumor tissues, skin SCD expression is elevated." (PMID 31316083, 2019). "In vitro experiments suggested that SCD strongly promoted tumour cell proliferation and invasion." (PMID 30592142, 2019). "SCD-1 knockdown contributed to inhibition of aggressive phenotype in tumor cells may depend on the reduction of synthesized fatty acid and attenuation of AKT-mTOR pathway." (PMID 28399876, 2017). "Indeed, SCD silenced tumours were almost undetectable 25 days after doxycyline treatment was initiated." (PMID 27042297, 2016). "In combitional metabolite and gene expression profile study of tumor and non-tumor tissues showed changes in the expression of stearoyl-CoA-desaturase (SCD) associated with HCC." (PMID 27458508, 2016). "Finally, silencing of SCD in prostate orthografts efficiently blocked tumour growth and significantly increased animal survival." (PMID 27042297, 2016). "Having shown that SCD is important to control lipid provision under conditions that resemble the metabolic microenvironment of tumours, we next investigated whether SCD expression is also essential for tumour growth." (PMID 27042297, 2016). "Finally, SCD is essential for tumour cell growth within the metabolic restraints of the tissue that they arise in." (PMID 27042297, 2016). "Furthermore, the poly-unsaturated DG population, which was selectively upregulated in tumours, was reduced when SCD was ablated." (PMID 27042297, 2016). "Consequently, inhibition of SCD suppresses tumor growth by increasing apoptosis and ferroptosis." (PMID 39543650, 2024). "Unexpectedly, even though blocking CES1 activity impairs mitochondrial function and reduces SCD levels, both of which might vitally affect the growth and proliferation of tumor cells, we only observed a mild effect of cell apoptosis in WWL229-treated and CES1-KO HepG2 cells." (PMID 36472914, 2023). "Consequently, genetically modified xenograft models (SCD gene knockdown or overexpression), as well as pharmaceutical inhibition of SCD activity, are commonly used to study the role of this enzyme family in tumor development and progression." (PMID 37373069, 2023). "Taken together, these results demonstrated that CAF-derived lipids or exogenous lipids could compensate for low SCD expression and then alter lipid composition, further influencing cell membrane fluidity, which plays a profound role in promoting tumor growth and metastasis." (PMID 35342344, 2022). "However, up to now, tumor hypoxia in ccRCC has not been associated with the induction of SCD-1 and its consequent modification of the tumor lipidomic profile." (PMID 34199164, 2021). "The notable effect of the inhibitor on tumor vasculature has potential therapeutic value because normalization of tumor vasculature may allow enhanced delivery of other anticancer drugs to synergize with SCD inhibition." (PMID 33568479, 2021). "Likewise, over the years, SCD has been reported to have a determinant role in various types of tumor, including lung, breast, prostate, colon, kidney, thyroid, and lymphoma, and its inhibition has proven efficacy in suppressing different tumor aspects." (PMID 33050166, 2020). "SCD represents the biosynthetic source of components for a plethora of lipids, such as the precursors oleic and palmitoleic acids, the most abundant monounsaturated fatty acids (MUFAs) with central roles in tumor progression, allowing cellular membrane biogenesis, energy storage, and cell signaling." (PMID 33050166, 2020).
tumor (continued). "In contrast to tumor-enriched lipolysis and fatty acid synthesis enzymes that do not require oxygen, fatty acid metabolic genes that require molecular oxygen are depleted in the tumor region, including fatty acid desaturation (SCD, FADS2) and oxidation (ACSL1)." (PMID 32103057, 2020). "During tumor development, lipid associated alterations include an increase in lipogenic enzymes expression such as fatty acid synthase (FASN), acetyl carboxylase (ACC), stearoyl-CoA desaturase (SCD), ATP citrate lyase (ACLY), and an increase in the synthesis and uptake of cholesterol." (PMID 30913248, 2019). "Finally, silencing of SCD resulted in efficient reduction of tumour growth in prostate orthografts." (PMID 27042297, 2016). "Moreover, SCD expression correlated with tumour grade and was indicative of disease relapse." (PMID 27042297, 2016). "To examine whether the MAC16 tumour-burden affects the lipid storing ability of adipose tissue through inhibiting fatty acid and triglyceride synthesis, we compared the expression of SREBP-1c target – genes encoding lipogenic enzymes, ACC, FAS, SCD-1 and GPAT." (PMID 17047651, 2006). "Compared with normal controls, the relative mRNA expression levels of NOX4, SCD, and TIMP1 were significantly higher in tumor tissues, while those of AQP8 and NR5A2 were significantly lower." (PMID 41438584, 2026). "We demonstrate that hypoxia upregulates the key desaturase, stearoyl-CoA desaturase-1 (SCD1), and the lipid droplet (LD) protein PLIN2, thus promoting lipid metabolic adaptation, cell proliferation, migration, and tumor growth." (PMID 42292857, 2026). "Studies have found that a variety of key metabolic enzymes involved in fatty acid synthesis and oxidation are upregulated in breast cancer and play an important role in tumor growth, such as SREBP1, ACC1, FASN, SCD, and ELOVL1." (PMID 40002387, 2025). "Stearoyl-CoA desaturase (SCD) converts saturated FAs into monounsaturated fatty acids (MUFAs), thereby enhancing lipid utilization within the tumor microenvironment." (PMID 40723225, 2025). "Desaturases such as stearoyl-CoA desaturase (SCD) and fatty acid desaturase-2 (FADS2) are frequently dysregulated across tumor types." (PMID 41465101, 2025). "DUSP9‐overexpressing tumours showed higher levels of DUSP9, SCD, NANOG and Ki67, whereas DUSP9‐knockdown tumours displayed reduced expression of these markers." (PMID 41383134, 2025). "Lung fibroblasts enhance tumor cell proliferation and metastasis by secreting cathepsin B (CTSB), which upregulates stearoyl CoA desaturase 1 (SCD1) expression and subsequently increases fatty acid content in tumor cells." (PMID 40765822, 2025). "Another SCD inhibitor, BZ36, interferes with de novo lipogenesis and carcinogenic signaling in a prostate cancer mouse model, leading to inhibition of tumor growth." (PMID 41421797, 2025). "We also focus on discussing specific enzyme-targeted anti-tumor inhibitors in the FA metabolic pathway, with a particular emphasis on targeting FASN and SCD, which have gained broad attention." (PMID 41421797, 2025). "Preclinical experiments confirm that targeting ferroptosis-related pathways (such as the USP7/SCD axis and ABCC2-mediated glutathione efflux) effectively inhibits tumor growth and metastasis." (PMID 40861444, 2025). "In tumor tissue, CAF-derived supernatant provided fatty acids to CD4+ TILs, which increased the expression of SCD and oleic acid (OA) content." (PMID 39543650, 2024). "Since FAs are limited in the human body for fast-growing tumors, many tumor cells synthesize unsaturated FAs by de novo synthesis pathway, modulated by several key enzymes such as ACLY, SCD, FASN, and ACC." (PMID 38560498, 2024). "Stearoyl-CoA desaturase (SCD) converted saturated fatty acids (SFAs) into unsaturated fatty acids (UFAs), which are part of fatty acids, an important source of energy in tumor cells." (PMID 38355626, 2024).
tumor (continued). "We discovered that SCD in CD4+ T cells promote Th1 cell polarization and activation of the cytotoxic effect in CD8+ T cells within the tumor immune microenvironment." (PMID 39543650, 2024). "Our findings revealed that the SCD gene is highly expressed in PRAD patients, and the SCD protein promotes the proliferation, invasion, and migration of PRAD tumor cells." (PMID 39351232, 2024). "Our findings demonstrated that SCD overexpression is correlated with PRAD progression, as well as the changes in the tumor immune microenvironment." (PMID 39351232, 2024). "We come to a conclusion that the proposed modulatory model of IGF2BP3 in CC, in which IGF2BP3 regulates the methylation of SCD mRNA by IGF2BP3-METTL14 complex, thereby accelerating lipid metabolism and tumor progression in CC." (PMID 38355626, 2024). "Quantitative analysis of the Western blot data visually confirmed the differential expression patterns observed, with higher levels of SCD, SUMF2, and KDEL2R in tumor tissues, and higher levels of TM4SF1 in paracancerous tissues." (PMID 39104534, 2024). "Treatment with SCD inhibitors was found to disrupt the balance between MUFA and SFA and reduce the survival rate of tumor cells." (PMID 38541630, 2024). "The MUFA membrane content is also partly regulated by SCD enzymes and SCD enzymes are differentially expressed in cancerous tissue, due to which the conversion rate of SFAs into MUFAs may be altered, leading to changes in the amount of MUFAs present in the membranes of tumor cells." (PMID 36830818, 2023). "A range of SCD inhibitors is now available (e.g., A939572, SSI-4, g-PPT, MF-438), and most of these have been shown in preclinical models to produce stronger anti-tumor effects when combined with chemotherapy and targeted therapies." (PMID 37700339, 2023). "For example, decreased stearoyl-CoA desaturase (SCD) leads to imbalance between unsaturated and saturated fatty acids that can slow tumor growth." (PMID 37298551, 2023). "Consistent with SCD playing a critical role in HCC tumor growth, Bansal et al51 demonstrated the inverse relationship between SCD gene expression patterns and HCC tumor differentiation." (PMID 39132609, 2023). "The IHC staining of the xenograft tumor tissues showed that CREB1 knockdown decreased the level of 4-HNE, a marker of lipid peroxidation, and that SCD overexpression restored the CREB1 knockdown effect." (PMID 37957645, 2023). "At the same time, that of FABP5, SCD, and CCL20 were upregulated considerably in TCGA HCC compared with non-tumor tissues." (PMID 36950134, 2023). "aHSC release 12-HHTrE in a manner dependent on SCD and CYP1B1 and their conditioned medium reproduces the LTB4R2-mediated tumor-promoting effects of 12-HHTrE in HCC cells." (PMID 37156770, 2023). "Among the fatty acid desaturase (FADS) gene superfamily, stearoyl-CoA desaturase has been demonstrated to play a significant part in tumor malignant behaviors." (PMID 36788618, 2023). "Subclustering analysis of the tumor, myoepithelial, and macrophage populations identified proliferative (TOP2A +), SCD +, and S100A8+ tumor cells, although these populations were not spatially distinct." (PMID 38114474, 2023). "However, the downregulation of SCD did not cause an obvious decrease in tumor growth in vivo." (PMID 35342344, 2022). "Instead of relying on the canonical SCD pathway for fatty-acid desaturation, tumor cells appear to exploit a different enzyme, FADS2, and upregulate this alternative route when SCD is inhibited." (PMID 35883589, 2022). "Similar to SCD, FADS1 expression was lower in the growing tumor area compared to the peritumoral area and in the necrotic core compared to the peritumoral area." (PMID 32392704, 2020). "In the growing tumor area, FADS1, FADS2, SCD, and SCD5 expression positively correlated when using the B2M gene as reference." (PMID 32392704, 2020).
tumor (continued). "Dox-H mice showed a significant increase in the protein expression of SCD-1 and ATGL compared to vehicle-H (SCD-1, p < 0.05 and ATGL, p < 0.01) and Dox-L mice (SCD-1, p < 0.05 and ATGL, p < 0.01), in tumor tissue." (PMID 32257945, 2020). "The results indicated that RA-XII strongly inhibited tumor growth and lipogenesis (triglycerides and lipid droplets) in HepG2 cells, and the expression of key factors involved in lipogenesis (SREBP, SCD, FASN) was also obviously downregulated." (PMID 31083642, 2019). "Regarding miRs expression, miR-19b-1-3p kept its tumor-suppressor role in murine CRC-like organoids, also reported as a good prognosis miRNA, able to target the protumorigenic ACSLs/SCD axis." (PMID 31339921, 2019). "The SCD inhibitor BZ36 and FASN inhibitor C75 have shown anti-tumor effects in a pre-clinical xenograft model." (PMID 31083642, 2019). "Recently, a new cell death pathway was attributed to betulinic acid in which cell death is induced through the inhibition of the stearoyl-CoA-desaturase (SCD-1), an enzyme that is overexpressed in tumor cells." (PMID 29337925, 2018). "Our previous data supported a role for the Stearoyl-CoA desaturase (SCD5) in protection against malignancy, whereby it appears to functionally modify tumor stroma impairing tumor spread." (PMID 29484133, 2018). "This study broaden the prognostic value of ABCA1, ACSL1, AGPAT1 and SCD genes, independently of CRC tumor stage, leading to future precision medicine approaches and “omics”-guided therapies." (PMID 29464044, 2018). "In clear cell renal cell carcinoma (ccRCC), SCD-1 expression was positively correlated with the TNM stage, grade of tumor cells, and lymphatic metastasis." (PMID 28399876, 2017). "Another promising target in the field is stearoyl-CoA desaturase (SCD), for which multiple studies have identified a crucial role in tumor growth." (PMID 27635066, 2016). "In the case of stearoyl-CoA desaturase, multiple SCD isoforms exist in the mice, and it is necessary to assay the expression of these SCD isoforms in different mouse tumor models." (PMID 24069385, 2013). "ACACB, ADH1B, and SCD, as key genes related to FAM, play important roles in tumor progression in PTC and may serve as potential therapeutic targets in PTC patients." (PMID 40084144, 2025). "The differential expression of ATP citrate lyase (ACLY), acetyl-CoA carboxylase alpha (ACACA), fatty acid synthase (FASN), SCD, and SREBF1 was further validated via RT‒qPCR subsequent to magnetic-based cell sorting of co-cultured H2228 and H3122 tumor spheroids." (PMID 40524253, 2025). "Notably, curcumin treatment suppressed the expression of lipid and polyamine biosynthetic enzymes (e.g., FASN, SCD, GLS), indicating a broad reconfiguration of tumor metabolic networks." (PMID 40557160, 2025). "For lipid metabolism, key enzymes such as ACC, FASN, SCD, and ACS are affected by lncRNAs, resulting in lipid uptake, storage, and catabolic reprogramming, through which cancer cells obtain important raw materials for tumor growth and progression." (PMID 38184562, 2024). "More importantly, IHC staining further verified at the clinical CRC sample scale that the density of LDHA and SCD was increased in tumor regions of obese CRC samples compared to the non-obese CRC samples." (PMID 38311726, 2024). "For example, the overexpression of acetyl coenzyme a synthase (ACSL1 and ACSL4) and sterol coenzyme a desaturase (SCD) induces epithelial-mesenchymal transition (EMT) in colorectal cancer, thereby enhancing the migratory and invasive capabilities of tumor cells." (PMID 38994204, 2024). "Hence, USP7/ZNF638/SREBP1C complex upregulates the expression of acetyl CoA carboxylase (ACACA), FASN, and stearoyl-CoA desaturase (SCD) to promote DNL and tumor initiation." (PMID 37176148, 2023). "Besides, CREB1 knockdown suppressed xenograft tumor growth in the presence of Imidazole Ketone Erastin (IKE), a potent FIN, and this effect was reversed by SCD." (PMID 37957645, 2023).